AMH (anti-Mullerian hormone)
Diseases named in the same sentence as AMH in open-access papers (continued):
Sharing a sentence is not in itself a finding about the gene and the disease.
endometriosis (continued). "We found the ovarian reserve and responsiveness of endometriosis patients were significantly lower, manifested by lower AMH, lower AFC, higher basal FSH, lower basal LH, and a significantly decreased number of retrieved oocytes." (PMID 37649072, 2023). "Those factors included age, pain score, laterality, size of the cyst, pre-operative AMH level, duration of operation, score, and stage of endometriosis." (PMID 35582413, 2022). "In some studies, AMH has been proven to be an important prognostic parameter in both treated and untreated patients because of endometriosis." (PMID 36294778, 2022). "GnRH-a treatment in endometriosis patients led to dynamic changes in the serum AMH levels, that is, ascent at 1 month (P = 0.05), and descent at 3 months (P = 0.02)." (PMID 35698127, 2022). "The levels of AMH in untreated patients are usually correlated with the extent of the endometriosis or its impact on the functionality of the active ovarian tissue." (PMID 36294778, 2022). "Next, the horizontal line and black points in the leave-one-out plot of TT, E2, AMH, menopause, endometriosis, leiomyoma, and PCOS crossed the zero line, suggesting potential heterogeneity." (PMID 36035116, 2022). "Our study using the univariate analyses indicate factors that affected AMH levels postoperatively including age, pain score, laterality, cyst size, pre-operative AMH levels, duration of surgery, rASRM score and endometriosis stage." (PMID 35582413, 2022). "Endometriosis and PCOS are thus associated with opposite levels of AMH, which also reflect diametric patterns in ovarian aging and menopause onset, as described in more detail below." (PMID 34295358, 2021). "In some pathologies, such as endometriosis or systemic lupus erythematosus, the relevance of pretreatment AMH levels for predicting the need for fertility preservation is unclear." (PMID 34501257, 2021). "In endometriosis, by contrast, lower LH relative to FSH is associated with lower AMH, signaling lower ovarian reserve and lower ovarian testosterone." (PMID 33854783, 2021). "There have been several preliminary pieces of research studying the effect of unilateral and bilateral laparoscopic surgery for endometriosis on AMH level after 3 and 6 months." (PMID 32972380, 2020). "In this research work, all studies focusing on the comparison of unilateral and bilateral laparoscopic surgery for endometriosis on AMH level after 3 and 6 months were systematically examined without time limitations and according to the PRISMA guidelines." (PMID 32972380, 2020). "According to this systematic review and meta-analysis study, the effect of bilateral laparoscopic surgery for endometriosis on AMH level was more than for unilateral laparoscopic surgery for endometriosis." (PMID 32972380, 2020). "The effect of bilateral laparoscopic surgery for endometriosis on AMH level reduction is more than unilateral laparoscopic surgery for endometriosis; moreover this reduction intensifies after 6 months." (PMID 32972380, 2020). "On the other hand, AMH levels in PF were significantly lower in women with endometriosis compared to those of control women [2.15 ± 2.13 (mean ± SD) vs. 4.40 ± 4.77 ng/mL, P = 0.0001]." (PMID 33263001, 2020). "The results of this study indicate that unilateral and bilateral laparoscopic surgery for endometriosis is effective on AMH level and the level decreases for both comparisons." (PMID 32972380, 2020). "In this study, we found significant inverse linear correlations between age and serum AMH and AMH in PF in women with endometriosis." (PMID 33263001, 2020). "Paired serum and PF AMH levels were examined in 90 women with advanced endometriosis (rASRM stage III, n = 30; stage IV, n = 60) and 32 control women." (PMID 33263001, 2020). "This research work aimed to identify the effect of unilateral and bilateral laparoscopic surgery for endometriosis on AMH levels after 3 months, and 6 months, using meta-analysis." (PMID 32972380, 2020).
endometriosis (continued). "Individual differences between AMH in PF and serum AMH were significantly lower in women with endometriosis [endometriosis −0.75 ± 2.35 (mean ± SD) vs. control 1.23 ± 4.01, P = 0.001]." (PMID 33263001, 2020). "The AMH level is reduced in both comparisons, and the effect of bilateral laparoscopic surgery for endometriosis on AMH level was more than for unilateral laparoscopic surgery for endometriosis." (PMID 32972380, 2020). "As endometriosis is detrimental to granulosa cells, we analyzed the expression of AMH in human granulosa cells." (PMID 32151056, 2020). "On the other hand, when we compare AMH in PF according to the presence of endometriosis, we found significantly lower AMH in PF in women with advanced endometriosis compared to those of control women." (PMID 33263001, 2020). "The results of this study demonstrate that unilateral and bilateral laparoscopic surgery for endometriosis is effective on AMH levels, and the level decreases in both comparisons." (PMID 32972380, 2020). "There is a significantly higher decrease in AMH after surgery for advanced endometriosis compared to early stage disease." (PMID 31824636, 2019). "It seems that we can use AMH level as a predictive marker of ovarian response to stimulation in patients with endometriosis and through which the best approach to individual treatment can be determined to increase their chances of fertility." (PMID 30775688, 2018). "In patients with stage 3 or 4 endometriosis who had lower serum AMH level significantly (p=0.001) less oocytes were retrieved (p=0.001) and less transferrable embryos (p=0.03) were achieved." (PMID 30775688, 2018). "Based on the results of this study, inverse relationship was found between the level of AMH and severity of endometriosis." (PMID 30775688, 2018). "From 11 patients with stage 3 and 4 endometriosis, 4 patients had less than normal AMH (36.4%), 7 patients had normal AMH (63.6%) and nobody had more than normal AMH." (PMID 30775688, 2018). "From 21 patients with stage 1 and 2 endometriosis, only one patient had less than normal AMH (4.7%), 18 patients had normal AMH (85.7%) and 2 patients had more than normal AMH (9.5%)." (PMID 30775688, 2018). "AMH levels were shown to decrease with age in untreated endometriosis patients (P < 1.0 × 10−5) but they were significantly lower in endometriosis compared to controls only in patients over 36 years old (P = 2.7 × 10−4)." (PMID 28791295, 2017). "Serum AMH values of 201 untreated endometriosis patients and 387 normal women were included in the analysis." (PMID 28791295, 2017). "Accordingly, serum AMH levels decreased faster with increasing age in endometriosis cases compared to controls." (PMID 28791295, 2017). "The results showed that AMH levels before surgery were significantly lower in endometriosis cases compared to controls (P = 1.0 × 10−3), in agreement with a similar analysis in a cohort of patients from Korea." (PMID 28791295, 2017). "We here report a study of AMH levels and ovarian reserve in 201 untreated endometriosis patients of Italian origin undergoing surgery for the first time." (PMID 28791295, 2017). "AMH is a reliable marker of ovarian reserve in endometriosis patients, and it can predict follicular density in women undergoing ovarian tissue cryopreservation." (PMID 28791295, 2017). "Serum AMH levels decreased with increasing age in patients and in controls as expected, but the decrease was faster in endometriosis cases." (PMID 28791295, 2017). "Serum anti-Müllerian hormone (AMH) concentration has been used to assess ovarian reserve in patients with endometriosis, especially when endometrioma surgery is involved." (PMID 27793163, 2016). "Patients with ovarian unilateral endometriosis also showed lower but insignificant median AMH levels compared to the control group (2.00; IQR: 2.80 vs. 2.84; IQR: 3.2; p = 0.182)." (PMID 26596960, 2015).
endometriosis (continued). "Lower serum AMH level was shown in endometriosis group with previous ovarian surgery, as compared with the endometriosis group without ovarian surgery, although it didn’t reach a statistical significance." (PMID 26359251, 2015). "Prior studies have analyzed pre- and post-operative serum AMH levels in patients with endometriosis." (PMID 26359251, 2015). "Remarkable declines in serum AMH were reported in patients with moderate to severe endometriosis, especially in those with bilateral endometriomas." (PMID 26359251, 2015). "When the plasmin-digested AMH was used on both endometriosis stromal and epithelial cells, an increase of pre-G1 phase treating with plasmin-digested AMH in both cell lines was detected, most marked in the epithelial cells." (PMID 24886254, 2014). "In our experimental setting, we have been able to demonstrate that cleaved AMH is effective in inhibiting cell proliferation in endometriosis cells." (PMID 24886254, 2014). "For example, ovarian response to gonadotropins is often attenuated in the setting of endometriosis, and serum AMH is reduced in fertility patients as a function of severity of the disease." (PMID 22136508, 2011). "Furthermore, identifying the precise clinical significance of serum AMH levels pre- and post-surgery in terms of predicting the probability of pregnancy would be most useful in patients with endometriosis with intentions for pregnancy." (PMID 40507534, 2025). "Based on those findings, surgery may be viewed as a valid option for young patients with severe endometriosis and a low AMH in whom the results of IVF are anticipated to be suboptimal." (PMID 40507534, 2025). "This narrative review examines how different endometriosis phenotypes and related surgeries affect AMH levels as well as explores whether pre- and post-surgical AMH can predict the reproductive outcomes in women seeking pregnancy." (PMID 40507534, 2025). "We also discuss if AMH levels pre- and post- endometriosis surgery may be useful in predicting the reproductive outcomes of patients with endometriosis and pregnancy intention." (PMID 40507534, 2025). "Endometriosis and its surgical treatment may damage ovarian reserve, as evidenced by lower levels of anti-Müllerian hormone (AMH) and antral follicle count, both of which can contribute to infertility." (PMID 40304605, 2025). "Furthermore, the peritoneal fluid of patients with advanced-stage endometriosis exhibited reduced AMH levels compared to controls." (PMID 40507534, 2025). "However, as we pointed out before, most of the background in AMH and endometriosis focuses on ovarian endometriosis, leaving peritoneal endometriosis relatively understudied." (PMID 40002761, 2025). "Consistently, AMH protein expression was decreased in ovaries in the presence of endometriosis." (PMID 40002761, 2025). "Studies have shown several factors that influence the success rate of IVF in patients with endometriosis, including the patient’s age, severity of endometriosis, anti-Mullerian hormone (AMH) level, oocyte and embryo quality, endometrial receptivity, and history of previous surgery." (PMID 39493123, 2024). "In the endometriosis group, most had AMH levels between 1–2 ng/mL (36%) or below 1 ng/mL (32%)." (PMID 39044926, 2024). "Our results revealed that ovarian cystectomy with different menstrual cycles may affect the rate of decrease in AMH levels after laparoscopic ovarian cystectomy in patients with endometriosis." (PMID 37370122, 2023). "AMH levels also decrease with increasing severity of endometriosis." (PMID 34295358, 2021). "The literature review also suggests that vitamin D supplementation can neither improve AMH production in women with PCOS nor does it reduce the risk of endometriosis." (PMID 32259002, 2020). "AMH levels were compared according to the presence of endometriosis." (PMID 33263001, 2020). "This study demonstrates that the level of AMH is visibly reduced after endometriosis laparoscopy." (PMID 32972380, 2020).
endometriosis (continued). "Therefore, the aim of this study was to identify the effect of unilateral and bilateral laparoscopic surgery for endometriosis on AMH level after 3 and 6 months using meta-analysis." (PMID 32972380, 2020). "Since these lesions may have different pathological entities, peritoneal endometriosis and AMH in PF may differently interact compared to other types of endometriosis." (PMID 33263001, 2020). "Although the cause of PF-specific alteration in AMH levels is unclear, lower AMH in PF in women with endometriosis may be related to pathophysiology of endometriosis." (PMID 33263001, 2020). "As peritoneal endometriosis expresses a specific receptor for AMH, lower AMH levels in PF of women with advanced endometriosis may be involved in the pathophysiology of peritoneal endometriosis." (PMID 33263001, 2020). "Interestingly, it has been shown that anti-Mullerian hormone (AMH) has a destructive effect on the endometrium and on endometriosis cells." (PMID 31416144, 2019). "However, in patients with endometriosis, 5 patients had less than normal AMH (15.6%), 25 patients had normal AMH (78.1%) and 2 patients had more than normal AMH (6.3%)." (PMID 30775688, 2018). "It seems that in patients with endometriosis, especially in severe cases because of ovarian conflict and reduced ovarian reserve, Anti-Mullerian Hormone (AMH) level could be reduced that could lead to lower response to assisted reproductive techniques (ART)." (PMID 30775688, 2018). "However, there was significant differences in AMH levels, the number of zygotes, metaphase II oocytes and obtained embryos in patients with stage 3 and 4 endometriosis compared with the control group." (PMID 30775688, 2018). "To test our primary hypothesis, that a correlation between AMH levels and follicle numbers could be established in endometriosis patients, we performed a regression analysis of AMH and follicle numbers including age and kit/laboratory as covariates." (PMID 28791295, 2017). "The AMH decrease was faster in endometriosis compared to controls (beta = 0.27, P = 4.0 × 10−4)." (PMID 28791295, 2017). "Considering the entire dataset, including the endometriosis patients, a statistically significant correlation was observed between AMH residual levels and the numbers of primordial follicles (beta = 0.3; P = 0.04): lower AMH residual levels corresponded to lower numbers of primordial follicles." (PMID 28791295, 2017). "Even though a limited sample size was analyzed, we showed that AMH might be used as a marker of ovarian reserve in endometriosis cases." (PMID 28791295, 2017). "The analysis of a larger cohort of patients could definitively add significance to the study, although our data already indicate that AMH represents a reliable marker of ovarian reserve in untreated endometriosis patients." (PMID 28791295, 2017). "In cases of advanced endometriosis with severe adhesions, recovery of serum AMH levels might prove difficult because of the damage to the mesosalpinx caused by adhesiolysis." (PMID 27793163, 2016). "At the out-patient department, clinicians often encounter this question: whether underlying endometriosis or previous ovarian surgery plays a more important role for the poor serum AMH level in patients with endometriosis." (PMID 26359251, 2015). "There was a noticeable trend of decreasing serum AMH from control group to endometriosis group." (PMID 26359251, 2015). "Changes in serum AMH level in patients with endometriosis have been well-documented." (PMID 26359251, 2015). "Moreover, this cleaved form of AMH is able to inhibit most of the CYP19 activity in endometriosis cells, as it has been already shown for cultured granulosa lutein cells." (PMID 24886254, 2014).
endometriosis (continued). "Treatment of endometriosis stromal and epithelial cell growth with AMH was able to induce a decrease in the percentage of cells in S phase and increase percentage of cells in G1 and G2 phase; coherently, decreased cell viability and increased percentage of cells death fraction was observed." (PMID 24886254, 2014). "Leaving from this background, we decided to deeply investigate the potential role of AMH in regulating cell viability and proliferation of endometriosis cells, taking advantage of an in vitro model of epithelial and stromal endometriosis cells, recently generated in our laboratory." (PMID 24886254, 2014). "The data produced suggest a possible use of AMH as therapeutic agents in endometriosis." (PMID 24886254, 2014). "RT-PCR has been used to quantify the expression levels of AMH and AMH RII isoforms, as well as of cytochrome P450 in both endometriosis epithelial and stromal cells Effects of AMH and AMH-cleaved treatment in endometriosis cells were evaluated by flow-cytometry analysis." (PMID 24886254, 2014). "AMH expression in human endometriosis glands was evaluated by immunohistochemistry." (PMID 24886254, 2014). "A small decrease in percentage of cells in S and G2/M phases was observed with a concomitant increase of cells in pre-G1 phase.Various semi-quantitative RT-PCR have been used to quantify the expression levels of AMH and AMH RII isoforms in both endometriosis epithelial and stromal cells." (PMID 24886254, 2014). "Both endometriosis epithelial and stromal cells expressed mRNA for AMH and AMH RII." (PMID 24886254, 2014). "Importantly, a reduction in AMH following endometriosis surgery should not be equated with a definitive loss of fertility potential." (PMID 40507534, 2025). "By performing multivariate analysis, earlier studies indicated that the affecting factors could be laterality and duration of surgery 32; patients age, baseline AMH levels, and bilateral endometriomas 19; bilateral cyst, size of the cyst, and stage of endometriosis." (PMID 35582413, 2022). "When the influence of the patient and IVF characteristics on IR were assessed, it was seen that higher basal serum levels of P4 and AMH were associated with better IR in women with endometriosis, regardless of whether or not they had the treatment before IVF." (PMID 36294778, 2022). "However, in the endometriosis group, it is possible that the sample size was too small to yield a statistically significant difference for serum AMH level and age; these results may have been different if the sample size had been larger." (PMID 34803917, 2021). "The same study identified a significant difference when comparing AMH levels between patients with stage I/II and stage III/IV endometriosis (stage Ι/ΙΙ: 3.28 ± 1.93 ng/mL vs. stage III/IV: 2.38 ± 1.83 ng/mL, p < 0.01)." (PMID 40507534, 2025). "The presence of endometriomas, or ovarian cysts, is linked to decreased ovarian reserve, as evidenced by lower levels of anti-Müllerian hormone (AMH) and a reduced antral follicle count (AFC) in women with endometriosis compared to healthy controls." (PMID 39229427, 2024). "This study was conducted to compare the ovarian reserve, represented by the serum AMH levels, and surgical outcomes after SPA laparoscopy and RAL for the management of patients with endometriosis." (PMID 37510787, 2023). "The importance of GnRH agonists in the treatment of endometriosis is indispensable, which indicates that the utilization of a long protocol in the category of patients treated for endometriosis and with favorable levels of P4, AMH, and FSH may lead to favorable outcomes." (PMID 36294778, 2022). "The median serum AMH level was 3.77 ng/mL and all the patients were in stage III-IV of endometriosis according to rASRM." (PMID 35582413, 2022). "As secondary study aims, we also evaluated the predictive value of AMH, DHEAS, and 25-hydroxy vitamin D levels for the presence of endometriosis in this special patient population." (PMID 31416144, 2019).